CD79A (CD79a molecule)
Diseases named in the same sentence as CD79A in open-access papers (continued):
Sharing a sentence is not in itself a finding about the gene and the disease.
cancer (287 papers, 1973 to 2026). A tumor composed of atypical neoplastic, often pleomorphic cells that invade other tissues. "The HLM score was constructed based on six genes, AGXT, TRIB2, ELFN2, PCDHB10, CALCA, and CD79A, which have been previously reported to be associated with the tumorigenesis and progression of various cancer types, including CRC, as well as chemotherapy resistance." (PMID 38902737, 2024). "The cells were further annotated as specific cell type subpopulations according to the expression of classic markers, including T cells (CD3D+), myeloid cells (CD68+), endothelial cells (CD34+), hepatocytes (ALB+), B cells (CD79A+), and cancer-associated fibroblasts (CAFs) (ACTA2+)." (PMID 37383234, 2023). "The ExCy and Fujifilm’s mRNA transcripts in the Disease pathway were revealed by TCGA’s Cancer Gene Consensus analysis to be more likely mutated: MUC4, CDK4, and CD79A, ARAF, respectively." (PMID 40598203, 2025). "Through this analysis, we identified eight major cell types, namely B cell (CD79A), cancer cell (KRT5), cycling cell (MKI67), endothelial cell (VWF), fibroblast (COL1A1), mast cell (KIT), monocyte/macrophage (CD14) and T cell (CD3D)." (PMID 38279519, 2024). "Positivity to CD79a was also detected in the epithelial cells of simple and micropapillay carcinomas." (PMID 33919282, 2021). "In summary, we have demonstrated expression of the B cell receptor subunit, CD79a, on immature myeloid cells and MDSCs in multiple mouse models of cancer and different mouse strains." (PMID 24146823, 2013). "CD79a was found also on normal human immature BM myeloid cells and upregulated on peripheral MDSCs from cancer patients." (PMID 24146823, 2013). "In this study, we found that the human epithelial cancer cells expressed two forms of IgM (membrane bound and secreted) as well as CD79A and CD79B." (PMID 23251529, 2012). "From these clusters, five major cell types were identified via classical cell markers, including T cells (CD3E, CD8A, CD3D), B cells (CD19, MS4A1, CD79A), myeloid cells (CD14, CD68, LYZ), endothelial cells (PECAM1, VWF, CDH5) and cancer-associated fibroblasts (CAFs) (ACTA2, FAP, PDGFRB)." (PMID 39941131, 2025). "Many epithelial cells showed immunohistochemical positivity for CD79a as follows: weak positivity for CD79a in hyperplastic areas of the mammary gland epithelium; strong and diffused positivity to all the layers of epithelial cells in tubulopapillary and micropapillary carcinomas." (PMID 33919282, 2021). "For example, CD3E and CD2 were highly expressed in T cells, CD79A was highly expressed in B cells and KRT18 was highly expressed in cancer cells." (PMID 36681772, 2023). "The phenotype of cancer cells shows variable expression of CD20 and presents CD19+, CD79a+, CD10-, BCL2+, PAX5+, BCL6-, and MUM-1/IRF-4+." (PMID 32528871, 2020). "Known cancer genes such as EGFR, EZH2, or CCDN2 were frequently affected by duplications and other known cancer genes such as CDKN2A, RB1, KLK2, or CD79A were frequently affected by deletions." (PMID 32604718, 2020). "The phenotypes of cancer cells are CD20+, CD79a+, bcl2+, CD10–, bcl 6+/–, FOX-P1, and MUM-1/IRF-4 positive." (PMID 32528871, 2020). "YKL-40 gene expression was primarily increased in the fibroblast (gene annotation: COL1A, BGN, DCN), myeloid (gene annotation: CD68, LYZ, AIF1), cancer (gene annotation: EPCAM, KRT7, KRT18), and B-cell (gene annotation: CD79A, CD79B) populations in cancer tissue compared to healthy tissue." (PMID 35631632, 2022). "DLBCL has no specific immunophenotype for either canine or human cancers; however, they express pan-B markers including CD79a, CD21, CD45, CD20." (PMID 36125986, 2022). "Similar with CD3D and CD52, CD79A and CD37 can not only help us monitor specific T–B interactions, which is one of the major parts of the anti-cancer immune response, but can also provide us a new biomarker to evaluate the alteration of cancer microenvironment during tumorigenesis." (PMID 34575089, 2021).
cancer (continued). "Additionally, volcano plots of the differentially expressed genes in these cancers indicated that in the RAC1 low-expression group, the expression levels of B cell surface markers (such as CD19, CD79A, and MS4A1) and immunoglobulin-related genes (such as IGHG1 and CR2) were higher." (PMID 39898257, 2025). "For example, there was an increase in the methylation of an immunologic marker gene CD79A, a decrease in methylation of a tumorigenic modulation gene DICER1, and a decrease in methylation of SLC25A1, a critical gene in mitochondrial homeostasis that is highly upregulated in cancer." (PMID 37138315, 2023). "Here we show that the B cell receptor adaptor molecule CD79a is unexpectedly expressed on immature bone marrow myeloid cells, and is upregulated on MDSCs generated in multiple different mouse models of metastatic but not non-metastatic cancer." (PMID 24146823, 2013). "We consistently identified a population of CD79A+CD27−IgD− B cells, also known as double-negative B cells, a rare subset of B cells not previously characterized in malignant tumors." (PMID 29448960, 2018). "The phenotypes of cancer cells are CD20+, CD79a+, CD5−, CD10+/−, bcl 6+, and MUM-1/IRF-4 negative." (PMID 32528871, 2020).
bacterial infections (74 papers, 2005 to 2025). "However, the candidates commonly used for adaptive immune cell characterization, such as CD79a and IgM for B cells and CD3 and CD4 for T cells, were minimally influenced by bacterial infection." (PMID 39011038, 2024).
hematologic malignancies (11 papers, 2008 to 2024). "As an example of an event both predicted by AbSplice and called by FRASER, we showcase CD79A, a well-known oncogene frequently affected by somatic mutations in hematologic malignancies." (PMID 38769532, 2024).
CD79A also shares sentences with these, for which no sentence is quoted: IgA nephropathy (366 papers); influenza (343); celiac disease (322); viral infection (238); asthma (205); inflammatory bowel disease (189); Allergy (143); rheumatoid arthritis (136); kidney disease (129); autoimmune thyroid disease (127); IgA vasculitis (123); glomerulonephritis (120); vasculitis (106); diabetes (101); type 1 diabetes mellitus (95); common variable immunodeficiency (94); bullous dermatosis (81); infectious disease (78); cholera (72); pneumonia (70); multiple myeloma (67); staphylococcus aureus infection (65); tuberculosis (65); Nephropathy (63); Hypertension (62); graft versus host disease (60); Obesity (60); pertussis (60); Crohn disease (59); dermatitis herpetiformis (58).
A further 949 diseases each share a sentence with CD79A in 58 papers or fewer.